ENSG00000252170
Synonyms: LOC124900503
Gene: Small nucleolar RNA gene on chromosome X (129,518,576 to 129,518,647, forward strand). Ensembl gene ENSG00000252170.
Gene Ontology:
Biological process: RNA processing
Cellular component: nucleolus
Homologues: Paralogues in human: SNORD112 (81% identical).